PRL (prolactin)
Diseases named in the same sentence as PRL in open-access papers (continued):
Sharing a sentence is not in itself a finding about the gene and the disease.
hyperprolactinemia (continued). "Neither the presence of hyperprolactinemia nor the positive immunohistochemical staining for prolactin was related to the reduction in IGF-1 or the rate of disease control, supposing that presence of PRL expression might not predict the response." (PMID 35612842, 2022). "Macroprolactinemia represents a state of hyperprolactinemia characterized by the predominance of big–big PRL (at least 60% of circulating PRL), and it should be suspected in asymptomatic individuals or those without the typical hyperprolactinemia-related symptoms." (PMID 35000899, 2022). "However, baseline prolactin levels, tumor size and the rate of hyperprolactinemia did not affect the remission rate." (PMID 35612842, 2022). "The results showed that vitamin B6 was comparable to cabergoline in reducing prolactin levels; however, implication of these findings for patients with migraine and other headaches related to hyperprolactinemia is not clear and hence needs further investigation." (PMID 34737888, 2021). "Furthermore, not all countries had formally excluded macroprolactin, and in some of the patients the diagnosis of hyperprolactinemia was based on randomly measured prolactin as not all countries measured prolactin concentrations regularly in every patient." (PMID 34441908, 2021). "It was not possible to determine the true prevalence of hyperprolactinemia in the whole cohort, since not all patients had routine measurements of prolactin or had data available on the number of patients with a non-elevated prolactin." (PMID 34441908, 2021). "Regarding the impact of hyperprolactinemia on cardiovascular function, the beneficial effects of E. angustifolia on heart rate and LDL-C level might be attributed to the decreased PRL level after E. angustifolia consumption." (PMID 34305584, 2021). "A limitation of the study is that our results cannot discriminate between high prolactin levels found in antipsychotic free patients with acute psychosis and drug induced hyperprolactinemia, because there was no measurement of prolactin levels before the onset of the current psychotic episode." (PMID 32017792, 2020). "Whether mild hyperprolactinemia should be corrected before initiating an in-vitro fertilization/intracytoplasmic sperm injection cycle (IVF/ICSI) has not been determined; this study aimed to examine how different levels of prolactin affect IVF outcomes." (PMID 32982975, 2020). "Interestingly, in all these cases the tumors failed to stain for prolactin despite the hyperprolactinaemia resolving after surgery." (PMID 32857272, 2020). "Hyperprolactinaemia was secondary to a giant leiomyoma with negative immunohistochemistry for PRL." (PMID 32857272, 2020). "Thus, we also speculated that the hemp-induced gonadotoxicity mediated through hyperprolactinemia and down-regulation of HPT axis might be reversed or prevented by inhibiting endogenous prolactin secretion with bromocriptine." (PMID 31208410, 2019). "Other causes of hyperprolactinemia include craniopharyngioma affecting the pituitary gland, non-pituitary tumors and PSIS that may affect the tuberoinfundibular pathway and increase PRL." (PMID 30396878, 2019). "In addition to PRL determination, TSH, free T4, and creatinine levels should be obtained to rule out secondary causes of hyperprolactinemia." (PMID 29768629, 2018). "Our group has shown that in a cohort of 119 active RA patients, the percentage of patients with hyperprolactinemia was comparable to the reported incidence in the general population, and plasma PRL levels did not correlate with any of the parameters reflecting disease activity." (PMID 28690611, 2017). "One of the shortfalls of this study is that accurate PRL levels are not available in some cases before BRC treatment; thus, we do not know whether pretreatment PRL level is associated with persistent hyperprolactinemia despite long-term DA therapy." (PMID 27999593, 2016).
hyperprolactinemia (continued). "With regard to other conditions, renal insufficiency can lead to moderate hyperprolactinaemia, and there are exceptional cases of non-pituitary tumours secreting prolactin, for instance renal cell carcinoma, gonadoblastoma, cervical carcinoma, non-Hodgkin lymphoma, and colorectal adenocarcinoma." (PMID 27716353, 2016). "However, if the sellar lesion is not a prolactinoma, but an NFPA (or other sellar lesion), prolactin levels remain at a similar level after dilution (hyperprolactinemia due to hypothalamic-pituitary disconnection)." (PMID 27533614, 2016). "Adjunctive aripiprazole treatment may be beneficial in reducing serum levels of prolactin and improving negative symptoms in schizophrenia patients with risperidone-induced hyperprolactinemia." (PMID 26448615, 2015). "A reduction in circulating prolactin levels was observed in a subgroup of patients in whom hyperprolactinaemia was unrelated to prolactinoma and, therefore, could not be associated with a decrease in tumour size and/or tumour apoplexy." (PMID 25239203, 2015). "One study indicated that hyperprolactinemia concurrence with hyperestrogenemia may have synergistic effects on SLE and estrogen could increase the production of anti-DNA autoantibody by B cell when exposed to prolactin." (PMID 25973434, 2015). "In this study, we retrospectively reviewed the patients with prolactinoma and non-functioning pituitary adenoma presented with hyperprolactinemia to confirm whether the serum prolactin cut-off value is definitive to distinguish them." (PMID 25142896, 2014). "Furthermore, DAs can normalize the serum prolactin level in patients with non-functioning pituitary adenoma presented with hyperprolactinemia by inhibition of the normal pituitary function, but there is no chance for tumor regression." (PMID 25142896, 2014). "Hyperprolactinaemia inhibits the hypothalamic-pituitary-gonadal axis, and hypogonadism secondary to hyperprolactinaemia may contribute to the negative effects of prolactin on cognition." (PMID 24586772, 2014). "The purpose of this study is to confirm whether the serum prolactin cut-off value is definitive to distinguish prolactinoma and non-functioning pituitary adenoma with hyperprolactinemia." (PMID 25142896, 2014). "However, none of the patients with hyperprolactinemia also had macroprolactinemia; all of the patients with macroprolactinemia (n=2) had PRL levels within the normal range, even before PEG treatment." (PMID 24312671, 2013). "However, two patients with macroprolactinemia had no hyperprolactinemia; their PRL levels were 12.04 and 15.85 ng/ml." (PMID 24312671, 2013). "In addition, in a study carried out by Leães and colleagues, of the total number of patients with positive IH to intracellular PRL, 27.8% presented hyperprolactinemia, 38.9% were positive for PRL-R, and 44.4% had neither of the two variables." (PMID 23317095, 2013). "A prolactin level was not measured in our patient but hyperprolactinemia could explain in part her delayed puberty." (PMID 23725039, 2013). "Finally, multiple researchers have noted hypoestrogenism in women with schizophrenia irrespective of prolactin level —that is, not just in those women with hyperprolactinaemia." (PMID 22966438, 2012). "Indeed, contradictory results have been published on the occurrence of hyperprolactinemia in multiple sclerosis patients, with some studies finding increased prolactin levels while others do not." (PMID 16928263, 2006). "Hyperprolactinemia in chronic kidney disease (CKD) without an underlying prolactinoma is fairly common, with worsening renal impairment correlating with higher prolactin levels, and several studies showing prolactin levels to be as high as around 100 μg/liter in ESRD patients." (PMID 40255723, 2025).
hyperprolactinemia (continued). "Previous studies have suggested elevated PRL in COVID-19 cases compared to non-infected patients; however, study heterogeneity is noted, leading authors to conclude that infection-related stress and not COVID-19 per se is possibly what primarily drives hyperprolactinemia." (PMID 39595974, 2024). "The decrease in prolactin secretion has been reported irrespective of the reason for prolactin excess, including in subjects with prolactinomas, empty sella syndrome, traumatic brain injury, drug-induced hyperprolactinemia, and in hyperprolactinemia of unknown origin." (PMID 39204081, 2024). "However, dopaminergic agonists may produce neutral effects on body weight in patients with hyperprolactinaemia signifying that obesity is mainly related to PRL excess rather than dopaminergic tone." (PMID 39663784, 2024). "Thus, the question arises whether hyperprolactinemia should be treated before and during assisted reproduction techniques (ART) as these procedures may overcome the detrimental effects on ovulation induced by high prolactin levels." (PMID 36678618, 2023). "Among those with hyperprolactinemia (n=207), patients with prolactin-negative adenomas (n=117) had larger tumors (p=0.003), and their tumors were more likely to invade into cavernous sinus (p=0.004) and sphenoidal sinus (p=0.003), compared to the patients with prolactin-positive adenomas (n=90)." (PMID 35154007, 2021). "Interestingly, although prolactin may be considered as a “stress hormone”, SA is probably not mediated by hyperprolactinaemia." (PMID 34360982, 2021). "These tumors do not produce prolactin; patients with macrotumors may have hyperprolactinemia but it is generally under 200 ug/L and is attributed to the interruption of dopaminergic neurons in the pituitary stalk, releasing the normal gland from tonic inhibition." (PMID 34067494, 2021). "Because PRL regulates its own secretion by short-loop negative feedback on dopamine releasing neurons 16, D2R downregulation may simply be a consequence of negative feedback rather than a trigger for hyperprolactinemia in bromocriptine resistant prolactinomas." (PMID 33173437, 2020). "Hyperprolactinemia is induced by antipsychotics with moderate to high affinity for D2 receptors; 4) it is not known whether measuring prolactin levels would be better than measuring the free levels of antipsychotics in the serum; and prolactin may be induced at low doses of antipsychotics." (PMID 34079927, 2018). "In addition to the known classical symptoms of hyperprolactinaemia, elevated levels of prolactin due to micro- or macroprolactinoma could have negative influences on metabolic parameters." (PMID 27525431, 2017). "The meta-analysis by Stubbs reports that neither PRL-raising AP use nor confirmed hyperprolactinemia contributed to the higher prevalence of low bone mass in schizophrenia; however, they conclude that heterogeneity between studies may underlie the absence of association." (PMID 26309037, 2015). "On the other hand, we could not perform analytic procedure of meta-regression for some other variables, including body mass index (BMI), body weight, duration of disease, serum prolactin levels, and % patients with hyperprolactinemia, because of lack of detailed data." (PMID 26632691, 2015). "These expression levels did not significantly change in response to hyperprolactinemia; however, populations of pro-B and immature cells from lupus-prone strains showed a decrease in the absolute numbers of cells with high PRL-receptor expression in response to PRL." (PMID 24454471, 2013). "Finally, prolactin levels should be measured irrespective of whether symptoms of SD are present or not to avoid potential long-term complications of “silent” hyperprolactinemia." (PMID 22190916, 2011).
hyperprolactinemia (continued). "On the other hand, it is also argued that elevated prolactin levels observed in patients with migraine could be an epiphenomenon of reduced dopamine activity, and headache relief after dopamine agonist treatment in patients with hyperprolactinemia does not correlate with prolactin lowering." (PMID 40168298, 2025). "Peripheral prolactin levels documented before IPSS were not available for 2 patients, thereby limiting our ability to assess the presence of hyperprolactinemia in these patients." (PMID 40765079, 2025). "However, the biomarker comparison data by PCOS status may help us confirm that some of the endocrinopathies (i.e., hypothyroidism as reflected by TSH levels, hyperprolactinemia as reflected by prolactin levels) are unlikely to be contributing to the possible PCOS cases identified." (PMID 41048429, 2025). "Prolactin (PRL), with its emphasis on hyperprolactinemia, is the only pituitary hormone for which lower limits of normal and reference intervals are not established." (PMID 38829475, 2024). "Subjects with idiopathic hPRL and anti-PRL autoantibodies have less clinical and serological activity of SLE and do not experience the classic symptoms of hyperprolactinemia such as menstrual disturbances and/or galactorrhea." (PMID 37299501, 2023). "In our cohort, PRL and TSH expression did not seem to correlate with hyperprolactinaemia or central hyperthyroidism clinically." (PMID 37851558, 2023). "As hyperprolactinaemia can occur in these gynaecological conditions, we have assessed all studies that evaluated the role of VAC on prolactin (PRL) regardless of the study outcome." (PMID 38075075, 2023). "This apoptosis peak coincides with the PRL peak and is absent in PRLRKO females, even before tumor formation (around 6 months old), although hyperprolactinemia has been evident since early ages." (PMID 36714572, 2022). "In our cohort, we found that the presence of clinical symptoms of hyperprolactinemia was one of the most predictive factors in diagnosing a cystic pituitary adenoma compared to an RCC, independent of serum prolactin level and lesion size." (PMID 34956896, 2021). "To date, high levels of prolactin in PWS adults have been reported anecdotally in both sexes, especially during therapy with psychotropic medications, and a thorough assessment of hyperprolactinemia in PWS is lacking." (PMID 34441908, 2021). "In other words, regardless of the natural retinal thinning and PRL changes that may come with age, older patients with moderately elevated PRL had greater RNFL thickness than patients with significant hyperprolactinemia." (PMID 35921360, 2022). "Treatment with APZ did not influence the serum prolactin level, and adjunctive treatment with APZ may ameliorate the hyperprolactinemia that occurs during monotherapy with other antipsychotics." (PMID 29209406, 2017). "In the FIGO classification, the effect of PRL on ovulation is not directly separated at various levels (hypothalamic, pituitary, or ovarian) of physiological and pathological (PCOS) regulation; in contrast, the WHO classification clearly considers the states of hyperprolactinemia in groups V and VI." (PMID 38396659, 2024). "Hence, in clinical settings, when physicians encounter a patient with asymptomatic hyperprolactinemia planning IVF/ICSI treatment, the serum PRL level may be not suppressed to an extremely low level if organic lesions are excluded." (PMID 32982975, 2020). "Neither medications nor further examinations are recommended if free PRL concentrations after precipitating macroprolactin with PEG are normal, because the biological activity of macroprolactin is low and pregnancy is possible without any treatment for hyperprolactinemia." (PMID 23304187, 2012).
breast cancer (350 papers, 1975 to 2026). A primary or metastatic malignant neoplasm involving the breast. "This, in turn, causes dysregulation of the sex hormone axis, prolactin imbalance, and insulin resistance, collectively promoting the initiation and progression of breast cancer." (PMID 42311680, 2026). "This case is intriguing and provides new evidence that resistant PRL-secreting PitNETs can be associated with the development of breast cancer." (PMID 40160874, 2025). "Other studies have evaluated the associations between PRL levels and several well-confirmed breast cancer risk factors, such as parity and age at menarche." (PMID 40160874, 2025). "First, the association between prolactin secretion and the incidence of breast cancer remains controversial." (PMID 38554178, 2025). "Altogether, these results highlight that in mammary and breast cancer cells, the pro-differentiation effects of PRL/PRLR are closely linked to Hippo pathway promoting cell polarity and luminal linage differentiation." (PMID 40157909, 2025). "There is also a strong association with Prolactin signaling, which has previously been highlighted for its role in breast cancer and in colon cancer." (PMID 39858069, 2025). "Studies have found that traditional antipsychotic drugs can increase the risk of breast cancer, especially phyllodes tumors, and this has been associated with elevated prolactin levels." (PMID 40465597, 2025). "The theory of PRL as a causative factor in breast cancer was initially suggested on the basis of studies that included mouse models." (PMID 40160874, 2025). "Almost all evidence shows that high PRL levels are associated with a greater risk of breast cancer in postmenopausal women." (PMID 40160874, 2025). "Antipsychotics with D2 receptor blockade and associated prolactin elevation properties have been implicated in increasing breast cancer risk." (PMID 40465597, 2025). "With this in mind, higher levels of PRL are moderately associated with an increased risk of breast cancer." (PMID 40806464, 2025). "Other data in the literature show that a PRL value greater than 11 ng/ml measured within 10 years of diagnosis was associated with a greater risk of postmenopausal breast cancer in a prospective study." (PMID 40160874, 2025). "Observational studies in humans have indicated an association between breast cancer risk and circulating PRL levels within the upper normal range, although other studies have reported no such association." (PMID 40478803, 2025). "Given this increased risk of breast cancer, stronger warnings about this increased risk are warranted, and regular monitoring of prolactin levels and breast cancer screening should be part of the management plan for these patients." (PMID 39989981, 2025). "Elevated prolactin levels have been linked to increased breast cancer risk, with evidence suggesting a role in promoting both ductal and lobular cancer proliferation." (PMID 40465597, 2025). "The patient history of breast surgery before the prolactinoma diagnosis, and the high persistent PRL values despite the treatment are factors that have increased the risk of breast carcinoma development." (PMID 40160874, 2025). "Is it possible that we, as clinicians, unconsciously tend to prescribe prolactin-increasing antipsychotics to women at increased risk of breast cancer and prolactin-sparing antipsychotics to women less at risk?" (PMID 38687213, 2024). "The association between cumulative exposure to prolactin-increasing/prolactin-sparing antipsychotics and breast cancer was analyzed using conditional logistic regression, adjusted for comorbidities and co-medications." (PMID 38687213, 2024). "PRL-PRLR axis potentially associates with tamoxifen insensitivity in ERα-positive breast cancer cells." (PMID 38898487, 2024). "Large prospective cohort studies examining the association between prolactin levels and risk of breast cancers in humans have shown varied findings." (PMID 38595824, 2024).